VAV1 (vav guanine nucleotide exchange factor 1)
Diseases named in the same sentence as VAV1 in open-access papers (continued):
Sharing a sentence is not in itself a finding about the gene and the disease.
atherosclerosis (6 papers, 2013 to 2025). A disease characterized by the build-up of fatty material and calcium deposition in the arterial wall resulting in partial or complete occlusion of the arterial lumen. "Then, KEGG pathway analysis revealed that these genes were enriched in “lipid and atherosclerosis” (Ncf1, Eif2s1, Tank, Vav1, Nfe2l2), “B-cell receptor signaling pathway” (Blnk, Dapp1, Vav1), and “Fc gamma R-mediated phagocytosis” (Prkcg, Ncf1, Vav1)." (PMID 38952478, 2024). "This study used in vitro and in vivo experiments to demonstrate that Vav1/Rac1 signaling promotes the progression of atherosclerosis by affecting the migratory ability of foam cells in atherosclerotic plaques." (PMID 32190703, 2020). "Several studies have indicated important related functions for SYK and VAV1, suggesting that they play significant roles in atherosclerosis." (PMID 26742467, 2016). "Rahaman and colleagues have shown that the Rho-GEF Vav1 is involved in the formation of foam cells and thereby contributes to the development of atherosclerosis." (PMID 23372835, 2013). "The analysis revealed that a similar representation of the gene expression patterns of our candidate DEGs was seen in the dataset GSE28829, suggesting that VAV1, SYK, LYN and PTPN6 genes may play an important role in progression of atherosclerosis." (PMID 26742467, 2016). "Though we found similar expression patterns for upregulated VAV1 in both the qPCR and microarray analyses of ATH samples, VAV1 may not play a major role in the progression of atherosclerosis because its expression may be blocked at the translation phase." (PMID 26742467, 2016).
acute lymphoblastic leukemia (5 papers, 2017 to 2025). Leukemia with an acute onset, characterized by the presence of lymphoblasts in the bone marrow and the peripheral blood. "Loss of Vav1 induces T cell acute lymphoblastic leukemia (T-ALL) by increasing ICN1 signaling, and TLX inhibits Vav1 expression to stimulate ICN1 signaling in TLX+ T-ALL." (PMID 29136506, 2017). "Given the implication of Vav1 in T cell development and signaling, we next tested the biological activity of the mutant proteins using luciferase reporter-based c-Jun N-terminal kinase (JNK) and NFAT activity assays in the T cell acute lymphoblastic leukemia Jurkat cell line." (PMID 31888228, 2019). "Ablation of Vav1 promotes ICN1 signaling and the development of T cell acute lymphoblastic leukemia (T-ALL)." (PMID 29136506, 2017). "For example, VAV1 can unexpectedly play non-catalytic tumor suppressor functions in T-cell acute lymphoblastic leukemia (T-ALL) by controlling the levels of the active form of NOTCH1 (ICN1)." (PMID 34571765, 2021).
anaplastic large cell lymphoma (5 papers, 2013 to 2023). Anaplastic large cell lymphoma (ALCL) is a rare and aggressive peripheral T-cell non-Hodgkin lymphoma, belonging to the group of CD30-positive lymphoproliferative disorders, which affects lymph nodes and extranodal sites. "In vitro knockdown of Vav1 in anaplastic large cell lymphoma was sufficient to cause cell cycle arrest and apoptosis of these cells." (PMID 23342133, 2013). "VAV1 mutations have been also found at much lower frequency in other PTCL subtypes such as anaplastic large cell lymphoma (ALCL, 2% of total cases) and cutaneous T cell lymphoma (2% of total cases)." (PMID 35895495, 2022).
anemia (5 papers, 2015 to 2024). A reduction in the number of red blood cells, the amount of hemoglobin, and/or the volume of packed red blood cells. "At the same time, we found that Vav1-Cre/Shmt2fl/fl conditional knockout mice also exhibited significant splenomegaly, which is often caused by anemia." (PMID 39456851, 2024). "Although mice with embryonic deletion of Stat5 in all tissues have severe perinatal lethality, Vav1-Cre/+Stat5abfl/fl mice showed normal survival but with the diagnostic signs of Stat5 deficiency including anemia and lymphopenia." (PMID 26338970, 2015). "Cell counting of splenic cells revealed that the number of splenic cells in Vav1-Cre/Shmt2fl/fl mice was significantly higher than in the control group, consistent with the phenomenon of compensatory splenic enlargement caused by anemia." (PMID 39456851, 2024). "In this study, to explore the hematopoietic system abnormalities and anemia phenotypes arising from the conditional knockout of Shmt2, we utilized the Cre-lox recombination system to establish the Vav1-Cre/Shmt2fl/fl embryonic and adult mouse model." (PMID 39456851, 2024). "In order to investigate if anemia was caused by a malfunction in the erythroid lineage due to ILEI overexpression, we next examined the effects of Vav1-driven overexpression of the Fam3c/ILEI transgene on overall fitness and blood parameters." (PMID 37713409, 2023). "Additionally, levels of erythropoietin (EPO) in the peripheral blood serum of Vav1-Cre/Shmt2fl/fl mice were significantly elevated compared to those in control animals, indicating a compensatory response to the anemia." (PMID 39456851, 2024). "Mekhema null mutants died shortly after birth from a severe anemia, even though Vav1-icre expression occurs much earlier, around E11.5, in definitive HSCs (dHSCs), which are known to be involved in the generation of the definitive erythroid, myeloid, and lymphoid lineages." (PMID 34386488, 2021). "Hematological analysis of blood from Vav1-P1cKO mice revealed significant changes in RBC physiology without significant anemia." (PMID 26001274, 2015).
autoimmune disease (5 papers, 2009 to 2021). A disorder resulting from loss of function or tissue destruction of an organ or multiple organs, arising from humoral or cellular immune responses of the individual to their own tissue constituents. "Several polymorphisms in the VAV1 gene have been detected, and they may play a potential role in autoimmune diseases." (PMID 32380774, 2020).
lung adenocarcinoma (5 papers, 2015 to 2021). A carcinoma that arises from the lung and is characterized by the presence of malignant glandular epithelial cells. "Mutations in VAV1 identified in human lung adenocarcinoma also confer oncogenic activity that can be attributed to their enhanced Rho/Rac activity." (PMID 32158759, 2020). "The E59K and D51E oncogenic Vav1 point mutations identified from human lung adenocarcinoma resulted in truncation and overexpression of Vav1 with increased catalytic GEF activity for Rac1 activation." (PMID 32322580, 2020). "We chose to study the activity of Vav1 mutations from lung adenocarcinoma based on our previous studies." (PMID 30297765, 2018). "The effectors of module 3 – DNA methylations of UBIAD1 and VAV1 – are less well-known in lung adenocarcinoma." (PMID 26160836, 2015). "Interestingly, recent exome sequencing analysis identified mutations in VAV1 and the dual Ras/Rac GEF SOS1 in lung adenocarcinomas." (PMID 32158759, 2020).
ovarian carcinoma (5 papers, 2013 to 2023). A malignant neoplasm originating from the surface ovarian epithelium. "VAV1 expression was also reported in 59% (52/88) of ovarian cancer, esophageal squamous cell carcinoma (ESCC), human gastric cancer, and sonic hedgehog (SHH) subgroup medulloblastoma (MBSHH) tumors." (PMID 37174676, 2023). "In particular, overexpression of Vav1 in ovarian tumor-derived cells induces down-regulation of E-cadherin and up-regulates Snail and Slug, suggesting the use of this protein as a potential therapeutic target to prevent metastasis of ovarian cancer." (PMID 24962430, 2014). "Interestingly, a recent work highlighted a role for Vav1 in Epithelial Mesenchymal Transition (EMT) in ovarian cancer and it has been demonstrated that β-catenin might participate in this process." (PMID 25426554, 2015). "Concerning the prognostic value of the ectopic expression of Vav1 in solid tumors, it was reported to be inversely correlated with positive prognosis of PDA patients and associated with decreased survival rates in early-stage patients affected by epithelial ovarian cancer." (PMID 24962430, 2014).
pancreatic adenocarcinoma (5 papers, 2014 to 2025). "In this cell model, we found that Vav1 is essential for the ATRA induced decrease of the adhesion molecule EpCAM, known to be a marker of pancreatic adenocarcinoma stem cells." (PMID 33165749, 2021).
T-cell acute lymphoblastic leukemia (5 papers, 2017 to 2024). Acute lymphoblastic leukemia of T-cell origin. "On the other hand, it has been shown that wild‐type VAV1 can play tumor suppresor roles in other tumor types such as TCR‐negative T cell acute lymphoblastic leukemia." (PMID 35895495, 2022). "Thus, the transcriptional silencing of the VAV1 gene in some clinical subtypes of T cell acute lymphoblastic leukemia has been shown to be essential to eliminate the tumor suppressor activity of Vav1 against the Notch1 pathway." (PMID 31100928, 2019). "VAV1 silences NOTCH1 signaling and suppresses T cell acute lymphoblastic leukemia by promoting the degradation of the intracellular domain of NOTCH1 (ICN1) through ubiquitination and proteasomal degradation." (PMID 39200159, 2024).
B cell lymphoma (4 papers, 2008 to 2023). "VAV1 is frequently mutated and overexpressed in hematopoietic malignancies and various cancers and is accompanied by B-cell lymphoma." (PMID 35957889, 2022). "Epithelial cells expressing VAV1 secrete CSF-1 and possibly other cytokines that influence the development of B-cell lymphoma." (PMID 37174676, 2023). "Nevertheless, B-cell lymphomas developed in various organs, such as lung, liver, pancreas, and spleen, adjacent to VAV1-expressing epithelial cells." (PMID 37174676, 2023). "Surprisingly, overexpressing Vav1 in epithelial tissues induced chronic inflammatory reactions eventually leading to B-cell lymphomas development." (PMID 35326399, 2022). "It was found that there is potential crosstalk between epithelial cells of VAV1 (which secrete CSF-1) and lymphocytes expressing CSF-1R, which leads to B-cell lymphoma." (PMID 35957889, 2022). "Based on this knowledge, we expected the CSF-1 receptor to be expressed on monocytes within the B-Cell lymphomas identified in the Rosa Vav1 transgenic mice." (PMID 35326399, 2022). "We show here, for the first time, that expression of Vav1 in the epithelial tissue compartment leads to generation of B-cell lymphomas in various organs such as lungs, liver, pancreas and spleen." (PMID 35326399, 2022). "Since Vav1 is physiologically expressed in the hematopoietic system, it was expected that the development of B-cell lymphomas in the different organs stems from the extra expression of Vav1 in this system due to the contribution of the transgenic human Vav1." (PMID 35326399, 2022). "Taken together, our results suggest a potential cross-talk between epithelial cells expressing Vav1, that secrete CSF-1, and the lymphocytes that express CSF-1R, thus leading to the generation of B-cell lymphomas." (PMID 35326399, 2022). "As demonstrated by IHC of lung, liver and pancreas sections with anti-Vav1, anti-CSF-1R and anti-CSF-1 Abs, while CSF-1R is expressed in cells within the B-cell lymphoma, the ligand is expressed in the epithelial tissue where transgenic Vav1 is found." (PMID 35326399, 2022). "One of the likeliest possibilities that B-cell lymphoma develop in Rosa Vav1-transgenic mice is that Vav1-epithelial expressing cells secrete ligands that affect B-cell proliferation." (PMID 35326399, 2022). "In order to address the role of M2 phosphorylation in a more physiological context, we next monitored the coassembly with Fyn and Vav1 and the phosphorylation of M2 in A20 cells, a mouse B cell lymphoma line expressing surface IgGs." (PMID 18301737, 2008). "The activation of Vav1 by various pathogens, such as Helicobacter pylori and mycoplasma, that may drive MALT carcinogenesis was also suggested, yet it is not clear whether the B-cell lymphomas developed in Rosa Vav1 mice fit the same pathological classification." (PMID 35326399, 2022).
B-cell chronic lymphocytic leukemia (4 papers, 2009 to 2021). "Expression of Vav1 was also shown in hematological malignancies such as B cell chronic lymphocytic leukemia (B-CLL), occurring primarily in B-CLL patients with 13q chromosomal deletions." (PMID 23342133, 2013). "These analyses indicated that VAV1 mRNA was overexpressed in chronic lymphocytic leukemia, diffuse large B–cell lymphoma and smoldering myeloma relative to control cells." (PMID 20011522, 2009).
lymphopenia (4 papers, 2009 to 2024). Reduction in the number of lymphocytes. "As previously reported, Vav1–/– mice also manifested T–lymphopenia as inferred by the increased in the percentage of B220+ B–cells in the spleen." (PMID 20011522, 2009). "The combined inactivation of the Rasgrf2 and Vav1 loci did not aggravate the thymocyte developmental/selection defects or the T–cell lymphopenia induced by the single Vav1 gene deficiency." (PMID 20011522, 2009). "Thus, unlike the case of Vav1−/− mice, Vav1ΔC/ΔC animals do not develop T cell lymphopenia." (PMID 35895495, 2022).
Peripheral T Cell Lymphomas (4 papers, 2018 to 2022). "Mutations in the VAV1 guanine nucleotide exchange factor 1 have been recently found in peripheral T cell lymphoma and nonsmall‐cell lung cancer (NSCLC)." (PMID 35895495, 2022). "The presence of the Vav1-Myo1f fusion protein (where the C-terminal SH3 domain of Vav1 is replaced by the SH3 of Myo1f) was recently reported in peripheral T-cell lymphomas (PTLC), a heterogeneous group of non-Hodgkin lymphomas frequently associated with poor prognosis." (PMID 31143189, 2019).
rheumatoid arthritis (4 papers, 2018 to 2024). A chronic, systemic autoimmune disorder characterized by inflammation in the synovial membranes and articular surfaces. "Our findings indicate that, among the three family proteins, Vav1 is probably the best therapeutic candidate for the treatment of T cell-dependent rheumatoid arthritis." (PMID 34205377, 2021). "In this study, we have demonstrated that Vav1 and Vav2 play specific roles in different types of rheumatoid arthritis models." (PMID 34205377, 2021). "This might be relevant in the context of human disease, since recent studies have revealed a possible link between a specific VAV1 SNP (rs2546133) and rheumatoid arthritis severity." (PMID 34205377, 2021). "Genetic evidence suggests that three members of the VAV family (VAV1, VAV2 and VAV3) of signal transduction proteins could play important roles in rheumatoid arthritis." (PMID 34205377, 2021). "Likewise, there is a correlation between four VAV1 SNPs (rs682626-rs2546133-rs2617822-rs12979659) and the development of a rheumatoid arthritis condition negative for antibodies to citrullinated circular peptides." (PMID 34205377, 2021).
T cell lymphomas (4 papers, 2021 to 2022). "For example, the RhoA-G17V mutation leading to increased activation of the RhoA-GEF Vav1 and a gain-of-function mutation in the RhoA-GEF Vav1 itself leading to increased RhoA activation, are found in T-cell lymphomas." (PMID 33906663, 2021). "Moreover, a gain-of-function mutation of Vav1 itself has been shown to be over-represented in T-cell lymphoma." (PMID 34359851, 2021). "In contrast to our “clean” tumour formation pattern, the expression of VAV1 mutants using a transgenic approach leads to the formation of a much complex spectrum of immature and mature T cell lymphomas." (PMID 35895495, 2022). "Furthermore, the authors identified 8.2 % of VAV1 mutations in 85 RHOA mutation-negative T-Cell lymphoma samples, and the resulting acceleration of mutated VAV1 protein phosphorylation and subsequent accelerated TCR signaling could also be suppressed by dasatinib." (PMID 35330161, 2022).
angioimmunoblastic T-cell lymphoma (3 papers, 2022 to 2026). A mature T-cell non-Hodgkin lymphoma, characterized by systemic disease and a polymorphous infiltrate involving lymph nodes and extranodal sites. "VAV1 can also contribute to cancer in angioimmunoblastic T-cell lymphoma (AITL), with somatic RHOAG17V mutations found in 50–70% of cases." (PMID 37174676, 2023). "Mutant RhoA G17V is a clinically significant yet historically undruggable oncogenic GTPase that drives angioimmunoblastic T-cell lymphoma through a neomorphic interaction with the guanine nucleotide exchange factor Vav1." (PMID 41986244, 2026).
Arthritis (3 papers, 2012 to 2021). Inflammation of a joint. "It is quite likely that the impact of the Vav1 deficiency in this type of arthritis is due to the critical role of this protein during the development and selection of T cells within the thymus." (PMID 34205377, 2021). "We show here that the specific elimination of Vav1 is sufficient to block the development of antigen-induced arthritis." (PMID 34205377, 2021). "However, our data suggest that Vav1 can also contribute to this type of arthritis through the regulation of the proliferation and the differentiation of effector T cells in post-thymic stages." (PMID 34205377, 2021). "Additionally, Syk and Vav1 expression levels correlated with the cumulative arthritis severity score (Pearson’s correlation coefficient of 0.8 and p=0.0006 for both genes)." (PMID 23249408, 2012). "Although B cells play critical roles in arthritis development, we could not find any proliferative or activation defect in Vav1–/– B lymphocytes." (PMID 34205377, 2021).
COVID-19 (3 papers, 2021 to 2024). A disease caused by infection with severe acute respiratory syndrome coronavirus 2. "Addition of C24D to fresh PBMCs from COVID-19 patients significantly increased VAV-1 phosphorylation (from 65.20 ± 3.99% to 78.73 ± 6.09%, p < 0.005)." (PMID 34414199, 2021). "In this short report, we demonstrated that treatment of PBMCs from ten hospitalized COVID-19 patients with C24D resulted in the reactivation of CD45 key-signaling molecules: Lck, ZAP-70 and VAV-1." (PMID 34414199, 2021). "We demonstrate in this Brief Report the effect of adding C24D to PBMCs obtained from ten hospitalized COVID-19 patients on the phosphorylation of Lck, ZAP-70 and VAV-1 proteins in the CD45 signaling pathway." (PMID 34414199, 2021). "Vav guanine nucleotide exchange factor 1(VAV1), the ABR activator of RhoGEF and GTPase (ABR), and the p21-activatedprotein kinase exchange factor beta (ARHGEF7) were GEFs found to beupregulated in mild/severe COVID-19 samples in our study." (PMID 39392878, 2024). "LAT, VAV1, ZAP70, and CARD11, as the key components of T-cell receptor, exhibited a significant decrease with severity in COVID-19, negative with G004246 and CATG00000032642.1." (PMID 35573725, 2022).
diffuse large B-cell lymphoma (3 papers, 2009 to 2023). "VAV1 overexpression was also associated with activation and higher proliferative activity of diffuse large B-cell lymphoma (DLBCL)." (PMID 37174676, 2023).
glioblastoma (3 papers, 2015 to 2025). The most malignant astrocytic tumor (WHO grade IV). "Thus, in this case, expression of Vav1 is linked to synergistic signaling cross-talk between cancer cells and infiltrating cells, a phenomenon that could have a role in the neoplastic process in glioblastoma tumors." (PMID 26353933, 2015). "The study used a primary culture of GBM7-Luc2-mKate2 human glioblastoma, a line of YT (YTwt) wildtype human NK cells, as well as lines created by us with overexpression of VAV1 protein with either CISH (YT–Vav1+CISH–/–) or B2M (YT–Vav1+B2M–/–) knockouts." (PMID 40071076, 2025).
myeloid leukemia (3 papers, 2014 to 2020). A clonal proliferation of myeloid cells and their precursors in the bone marrow, peripheral blood, and spleen. "Next, we investigated the accumulation of the hematopoietic cell specific Vav1 protein, one of the master regulators of myeloid leukemia cell differentiation." (PMID 32698503, 2020).